SLC35E4 (solute carrier family 35 member E4)
Description:
Putative transporter.
Tractability: Antibody: UniProt predicts a signal peptide or a membrane-spanning region. PROTAC: ubiquitination databases record sites on it.
Gene: Protein-coding gene on chromosome 22 (30,635,781 to 30,669,016, forward strand). Ensembl gene ENSG00000100036.
Subcellular location: Membrane
Subcellular location (Human Protein Atlas): Cytosol
Gene Ontology:
Molecular function: protein binding
Cellular component: membrane
Genetic constraint (gnomAD): Loss-of-function variants: 17 observed, 19.11 expected, observed/expected ratio (o/e) 0.89, 90% interval 0.61 to 1.33. The upper end of that interval is the gene's LOEUF score, 1.33, which puts it in group 5 of 6, group 1 being the genes least tolerant of losing a copy. Missense variants: 406 observed, 466.66 expected, observed/expected ratio (o/e) 0.87, 90% interval 0.8 to 0.94. Synonymous variants: 219 observed, 219.63 expected, observed/expected ratio (o/e) 1, 90% interval 0.89 to 1.12.
Homologues: Orthologues: chimpanzee SLC35E4 (99% identical), macaque SLC35E4 (98% identical), pig SLC35E4 (91% identical), rabbit SLC35E4 (88% identical), guinea pig SLC35E4 (86% identical), rat Slc35e4 (85% identical), mouse Slc35e4 (84% identical), dog OSBP2 (68% identical), zebrafish slc35e4 (49% identical), tropical clawed frog slc35e4 (47% identical), Drosophila melanogaster frc (15% identical), Caenorhabditis elegans sqv-7 (14% identical). Paralogues in human: SLC35E2B (21% identical), SLC35C1 (19% identical), SLC35E3 (18% identical), SLC35D3 (17% identical), SLC35H1 (17% identical), SLC35D1 (16% identical), SLC35E1 (16% identical), SLC35D2 (15% identical), SLC35D4 (12% identical).
Diseases named in the same sentence as SLC35E4 in open-access papers:
SLC35E4 is named in the same sentence as 3 diseases in open-access papers, as found by Europe PMC text mining. Sharing a sentence is not in itself a finding about the gene and the disease. The quoted sentences say what the papers report.
atherosclerosis (1 paper, 2024). A disease characterized by the build-up of fatty material and calcium deposition in the arterial wall resulting in partial or complete occlusion of the arterial lumen. "The gene list included well-known atherosclerosis-associated genes Serpina3,42Cemip,43Thbs1,44Lum,45 and Spp146,47 but also novel genes without previous association to SMC function in atherosclerosis, such as Anxa4, Cd276, Itih4, Myof, Pcdh11x, Rab31, Serpinb6b, Slc35e4, Slc8a3, and Spink5." (PMID 38289873, 2024). "Moreover, we identified several novel genes not previously linked to SMCs in atherosclerosis, such as Anxa4, Cd276, inter-alpha-trypsin inhibitor-4 (Itih4), Myof, Pcdh11x, Rab31, Serpinb6b, Slc35e4, Slc8a3, and Spink5." (PMID 38289873, 2024).
type 1 diabetes (1 paper, 2025). "Among the eight DE genes, PSME4 and NTPCR were shown to be DE in children progressing to type 1 diabetes, in earlier studies, and the promoter region of SLC35E4 was hypermethylated in children progressing to the disease before seroconversion." (PMID 41462339, 2025).
cancer (1 paper, 2024). A tumor composed of atypical neoplastic, often pleomorphic cells that invade other tissues. "In particular, there is limited information available regarding the involvement of SLC35E4, AKAP5, and RDH8 in malignancies; only a few bioinformatics studies have addressed their potential as prognostic predictors for cancer." (PMID 38561388, 2024).